AKR1C3 (aldo-keto reductase family 1 member C3)
Description:
Cytosolic aldo-keto reductase that catalyzes NADPH-dependent reduction of ketosteroids to hydroxysteroids. Displays broad substrate specificity with distinct positional and stereochemistry, primarily generating 17beta-hydroxysteroids, but also 3alpha- and 20alpha-hydroxysteroids. Produces potent androgens via classical and 'backdoor'/alternative pathways. In the classical androgen metabolic pathway (biosynthesis of 5alpha-dihydrotestosterone (5alpha-DHT) via testosterone), catalyzes the reduction of delta4-androstenedione to form testosterone. In the 'backdoor' androgen metabolic pathway (biosynthesis of 5alpha-dihydrotestosterone (5alpha-DHT) via pregnanes), reduces androsterone to 5alpha-androstane-3alpha,17beta-diol preceding 5alpha-DHT secretion. Reduces 5alpha-DHT to less potent androgen 5alpha-androstane-3alpha,17beta-diol, likely regulating ligand availability for androgen receptors. May contribute to the metabolism of adrenal-derived androgen precursors. Reduces 11-keto-4-androstene-3,17-dione (11KA4) and 11-keto-5alpha-androstane-3,17-dione (11K-Adione) into potent androgens 11-ketotestosterone (11KT) and 11-ketodihydrotestosterone (11KDHT), respectively. In estrogen metabolism, catalyzes the conversion of estrone to potent estrogen 17beta-estradiol. Acts as a prostaglandin (PG) F2alpha synthase. Displays 11-ketoreductase and 9,11-endoperoxide reductase activities and reduces PGD2 to 11beta-PGF2alpha and PGH2 to PGF2alpha. Also displays retinaldehyde reductase activity toward 9-cis-retinal. In vitro can efficiently catalyze bidirectional conversion between ketosteroids and hydroxysteroids using NADPH/NADP(+) or NADH/NAD(+) as cofactors. In vivo however, the reductase activity prevails since the major reducing cofactor NADPH inhibits NAD(+)-dependent oxidase activity. In addition, it is able to reduce in vitro various carbonyl compounds like menadione, phenanthrenequinone and nitrobenzaldehyde (By similarity).
Synonyms: DD3; PGFS; HSD17B5; KIAA0119; DDX; HAKRB; HA1753; HAKRe; hluPGFS
Tractability: Small molecule: a structure with a bound ligand is known; a high-quality ligand is known; it has a high-quality binding pocket; it belongs to a druggable protein family. PROTAC: ubiquitination databases record sites on it; its protein half-life has been measured; a small molecule that binds it is known.
Target class: Enzyme; Oxidoreductase
Chemical probes: CHEMBL1443272, CHEMBL2172076, UNMCK90
Gene: Protein-coding gene on chromosome 10 (5,035,354 to 5,107,686, forward strand). Ensembl gene ENSG00000196139.
Subcellular location: Cytoplasm
Subcellular location (Human Protein Atlas): Cytosol; Nucleoplasm; Endoplasmic reticulum; Nucleoli fibrillar center
Pathways (Reactome):
Metabolism: Synthesis of Prostaglandins (PG) and Thromboxanes (TX); Synthesis of bile acids and bile salts via 24-hydroxycholesterol; Synthesis of bile acids and bile salts via 27-hydroxycholesterol; Synthesis of bile acids and bile salts via 7alpha-hydroxycholesterol
Sensory Perception: Retinoid metabolism and transport
Signal Transduction: RA biosynthesis pathway
Gene Ontology:
Molecular function: 15-hydroxyprostaglandin-D dehydrogenase (NADP+) activity; 17-beta-hydroxysteroid dehydrogenase (NADP+) activity; 3-alpha-hydroxysteroid 3-dehydrogenase [NAD(P)+] activity; 5-alpha-androstane-3-beta,17-beta-diol dehydrogenase (NADP+) activity; alcohol dehydrogenase (NADP+) activity; aldose reductase (NADPH) activity; all-trans-retinol dehydrogenase (NAD+) activity; androsterone dehydrogenase [NAD(P)+] activity; Delta4-3-oxosteroid 5beta-reductase activity; estradiol 17-beta-dehydrogenase [NAD(P)+] activity; ketoreductase activity; ketosteroid monooxygenase activity; oxidoreductase activity, acting on NAD(P)H, quinone or similar compound as acceptor; oxidoreductase activity, acting on the CH-OH group of donors, NAD or NADP as acceptor; prostaglandin D2 11-ketoreductase activity; prostaglandin F synthase activity; prostaglandin H2 endoperoxidase reductase activity; protein binding; retinal dehydrogenase (NAD+) activity; testosterone dehydrogenase (NAD+) activity; testosterone dehydrogenase (NADP+) activity; all-trans-retinol dehydrogenase (NADP+) activity; bile acid binding; 17-beta-hydroxysteroid dehydrogenase (NAD+) activity; androstan-3-alpha,17-beta-diol dehydrogenase (NAD+) activity; and 1 more
Biological process: cellular response to calcium ion; cellular response to corticosteroid stimulus; cellular response to jasmonic acid stimulus; cellular response to prostaglandin D stimulus; cellular response to prostaglandin stimulus; cellular response to starvation; daunorubicin metabolic process; doxorubicin metabolic process; farnesol catabolic process; G protein-coupled receptor signaling pathway; keratinocyte differentiation; macromolecule metabolic process; male gonad development; negative regulation of retinoic acid biosynthetic process; positive regulation of cell population proliferation; positive regulation of endothelial cell apoptotic process; positive regulation of phosphatidylinositol 3-kinase/protein kinase B signal transduction; positive regulation of reactive oxygen species metabolic process; progesterone metabolic process; prostaglandin metabolic process; regulation of retinoic acid receptor signaling pathway; regulation of testosterone biosynthetic process; response to nutrient; retinal metabolic process; steroid metabolic process; and 7 more
Cellular component: cytoplasm; cytosol; extracellular exosome; nucleus
Genetic constraint (gnomAD): Loss-of-function variants: 30 observed, 30.37 expected, observed/expected ratio (o/e) 0.99, 90% interval 0.74 to 1.34. The upper end of that interval is the gene's LOEUF score, 1.34, which puts it in group 5 of 6, group 1 being the genes least tolerant of losing a copy. Missense variants: 399 observed, 337.86 expected, observed/expected ratio (o/e) 1.18, 90% interval 1.09 to 1.28. Synonymous variants: 140 observed, 125.38 expected, observed/expected ratio (o/e) 1.12, 90% interval 0.97 to 1.28.
Homologues: Orthologues: chimpanzee AKR1C3 (99% identical), macaque AKR1C1 (96% identical), zebrafish akr1a1a (41% identical), Drosophila melanogaster CG6083 (40% identical), Caenorhabditis elegans Y39G8B.1 (39% identical), zebrafish zgc:56622 (38% identical), Caenorhabditis elegans C07D8.6 (36% identical), Caenorhabditis elegans Y39G8B.2 (33% identical), zebrafish zgc:110366 (32% identical), Caenorhabditis elegans F53F1.2 (31% identical), tropical clawed frog XB5731323 (30% identical), tropical clawed frog XB5994047 (30% identical), and 10 more. Paralogues in human: AKR1C1 (88% identical), AKR1C2 (87% identical), AKR1C4 (84% identical), AKR1C8 (68% identical), AKR1D1 (56% identical), AKR1B1 (47% identical), AKR1B10 (47% identical), AKR1B15 (44% identical), AKR1E2 (43% identical), AKR1A1 (41% identical), KCNAB3 (26% identical), AKR7L (26% identical), and 4 more.
Diseases named in the same sentence as AKR1C3 in open-access papers:
AKR1C3 is named in the same sentence as 116 diseases in open-access papers, as found by Europe PMC text mining. Sharing a sentence is not in itself a finding about the gene and the disease. The quoted sentences say what the papers report.
prostate carcinoma (64 papers, 2010 to 2026). A carcinoma that arises from epithelial cells of the prostate gland. "AKR1C3 and ARv7 are highly implicated in the development of chemotherapeutic resistance to clinical ARSIs in advanced prostate cancer." (PMID 38684887, 2024). "The upregulation of AKR1C3 is associated with progression, aggressiveness, and drug resistance in prostate cancer." (PMID 38188684, 2023). "It has been demonstrated that a high expression of AKR1C3 is closely associated with the upregulation of stem cell markers during the transformation of prostate cancer into CRPC." (PMID 36794010, 2023). "The relevance of the aldo–keto reductase 1C3 (AKR1C3) and its promoter gene polymorphisms in prostate cancer and its catalytic significance in producing extra-testicular androgens including the more potent dihydrotestosterone (DHT) are known." (PMID 34997089, 2022). "Overexpression of AKR1C3 is usually associated with prostate cancer progression, aggressiveness, and resistance to AR-targeted therapies." (PMID 35646665, 2022). "In recent years, AKR1C3 has been implicated in the progression of prostate cancer, breast cancer, colon cancer and oropharyngeal squamous cell carcinoma, and contributes to therapeutic resistance in these types of cancers." (PMID 34065695, 2021). "AKR1C3 has already been implicated in therapeutic resistance via mediating intracellular ROS levels in several types of cancer, such as prostate cancer, ESCC, choriocarcinoma and leukemias." (PMID 34065695, 2021). "Elevated expression of AKR1C3 is associated with the progression and aggressiveness of prostate cancer." (PMID 31447885, 2019). "Aldo-keto reductase family 1 member C3 (AKR1C3) is a key steroidogenic enzyme that is overexpressed in prostate cancer (PCa) and is associated with the development of castration-resistant prostate cancer (CRPC)." (PMID 24571686, 2014). "In the prostate, AKR1C3 is up-regulated in localized and advanced prostate adenocarcinoma, and is associated with prostate cancer (PCa) aggressiveness." (PMID 21134280, 2010). "For example, AKR1C3, which encodes a prostaglandin synthase involved in androgen production, is significantly upregulated and associated with poor outcomes in hepatocellular carcinoma, prostate cancer, and pediatric T-cell acute lymphoblastic leukemia." (PMID 39001492, 2024). "These agents could be beneficial, e.g., in the treatment of prostate cancer, since AKR1C3 and 17β HSD3 are frequently linked to this condition, and malignant tumors are usually surrounded by a proinflammatory microenvironment." (PMID 32993084, 2020). "The enzyme is highly expressed in the prostate gland and previous studies indicate that genetic variation in the AKR1C3 gene may influence the prostate volume and risk of prostate cancer." (PMID 22888320, 2012). "We identified AKR1C3 as a potential key target associated with radioresistance and malignant progression through integrated bioinformatic analysis of RNA sequencing (RNA-seq) data from prostate cancer clinical samples in The Cancer Genome Atlas (TCGA) and Gene Expression Omnibus (GEO) databases." (PMID 41912503, 2026). "In our study, we examined the potential of natural AKR1C3 inhibitors in various prostate cancer cell lines and a three-dimensional co-culture spheroid model consisting of cancer cells and cancer-associated fibroblasts (CAFs) mimicking enzalutamide resistant prostate cancer." (PMID 32731472, 2020). "In a previous study, we demonstrated that prostate cancer cells become enzalutamide-resistant upon spheroid co-culture with CAFs, associated with increased production of pro-inflammatory cytokines and elevation of steroid biosynthesis with significant upregulation of AKR1C3 in particular." (PMID 32731472, 2020). "In summary, this study reveals the molecular mechanism by which AKR1C3 is involved in metabolic reprogramming to promote radioresistance in prostate cancer through PKM2/UBE2T." (PMID 41912503, 2026).
prostate carcinoma (continued). "With PROTAC 5 in hand, we first determined AKR1C3 inhibition activity and its ability to ameliorate the survival of 22Rv1 prostate cancer cells that express high levels of AKR1C37." (PMID 38684887, 2024). "Critically we showcase the potential of a PROTAC functionalized AKR1C3 degrader in providing significant degradation of AKR1C3 expression in 22RV1 prostate cancer cells." (PMID 38684887, 2024). "This first-generation degrader potently reduced AKR1C3 expression in 22Rv1 prostate cancer cells with a half-maximal degradation concentration (DC50) of 52 nM." (PMID 38684887, 2024). "Specific inhibitors of AKR1C1 (3-bromo-5-phenylsalicylic acid) and AKR1C3 (tolfenamic acid, indomethacin; phase I/II trial in prostate cancer, NCT02935205)) are also available." (PMID 39272833, 2024). "AKR1C3 plays a crucial role in androgen and steroid metabolism and is highly expressed in metastatic prostate cancer specimens and circulating tumor cells." (PMID 39834787, 2024). "B4GALT1 was identified as a unique tumor suppressor silenced by AKR1C3 activation, thereby facilitating castration-resistant prostate cancer progression." (PMID 39391236, 2024). "AKR1C3 which plays a key role in peripheral androgen biosynthesis was found to be increased by androgen deprivation in castrate-resistant prostate cancer." (PMID 39055885, 2024). "Aldo-keto reductase 1C3 (AKR1C3) is a protein upregulated in prostate cancer, hematological malignancies, and other cancers where it contributes to proliferation and chemotherapeutic resistance." (PMID 38684887, 2024). "PROTAC 5 exerts its effects to reduce cell viability of prostate cancer cells in direct correlation to AKR1C3 expression." (PMID 38684887, 2024). "AKR1C3 was shown to have an important role in the progression of prostate cancer and several selective inhibitors of AKR1C3 have shown antitumor activity." (PMID 37427784, 2023). "Despite AKR1C3’s impact in prostate cancer steroidogenesis, it is potential as a treatment in the clinic remains untapped." (PMID 37772993, 2023). "The present study demonstrated that the genistein inhibited prostate cancer cell growth via decreasing the expression of AKR1C3 both in vitro and in vivo." (PMID 36794010, 2023). "In prostate cancer, AKR1C3 is upregulated by androgen-deprivation therapy, which confers resistance to androgen receptor (AR) antagonists, such as enzalutamide." (PMID 38188684, 2023). "AKR1C3 promotes tumor growth in prostate cancer cells by increasing androgen production or activating AR-mediated signaling." (PMID 38188684, 2023). "AKR1C1 and AKR1C3 have both been shown to be greatly increased in bone marrow metastases when compared to prostate cancer primary tumor sites." (PMID 37484909, 2023). "It has been reported that the expression of steroidogenic enzymes such as AKR1C3 becomes upregulated following ADT for prostate cancer patients." (PMID 36794010, 2023). "Recent studies have demonstrated that AKR1C3 was overexpressed in various cancers such as breast cancer, prostate cancer and acute myeloid leukemia (AML)." (PMID 36845727, 2023). "Aldo-keto reductase family 1 member C3 (AKR1C3) plays an important role in prostate cancer (PCa) progression, particularly in castration-resistant prostate cancer (CRPC)." (PMID 36901944, 2023). "Particularly in prostate cancer, AKR1C3 is strongly expressed in the tumor and is expected to be a biomarker and therapeutic target." (PMID 36841845, 2023). "GEO data (GSE2443) were used to compare the expression of AKR1C3 in primary prostate cancer (androgen dependent, Gleasons 5-9, n=10) with that in prostate cancer after androgen ablation (AR-independent, n=10)." (PMID 36591491, 2022). "AKR1C3, a crucial androgenic enzyme, plays a role in recoding the AR signal transduction in prostate cancer." (PMID 36276091, 2022). "In mammary and prostate carcinomas, AKR1C3 interacts with the steroid and prostaglandin pathways and promotes tumor progression." (PMID 35953777, 2022).
prostate carcinoma (continued). "A total of 490 prostate cancer patients were selected, among which 245 had high AKR1C3 expression and 245 had low AKR1C3 expression." (PMID 36591491, 2022). "AKR1C3, as a crucial androgenic enzyme, implicates the androgen biosynthesis and promoting prostate cancer cell growth in vitro." (PMID 36591491, 2022). "HSD17B5, also known as AKR1C3, is expressed in peripheral tissues and can be a source of peripheral conversion in some disease states, including prostate cancer." (PMID 36555196, 2022). "Other AKR family members, such as AKR1C3 enhances radioresistance of prostate cancer cells via the MAPK pathway." (PMID 35953777, 2022). "AKR1C3, a crucial androgenic enzyme, can reprogram AR signaling in advanced prostate cancer and is involved in the production of aromatase substrates in breast cancer." (PMID 34336641, 2021). "Recently, AKR1C3 has been reported to be upregulated in many human tumors and identified as a prognostic marker in various cancers, including breast cancer, prostate cancer and colon cancer." (PMID 34065695, 2021). "Consecutive prostate cancer specimens revealed increased AKR1C3 expression during progression to CRPC." (PMID 35582223, 2020). "Our results show that the natural AKR1C3 inhibitor designated MF-15 achieves a significant inhibitory effect in enzymatic assays as well as anti-neoplastic effects in various prostate cancer cell cultures models." (PMID 32731472, 2020). "Castration also induces up-regulation of AKR1C3 in an orthotopic VCaP human prostate cancer xenograft and leads to tumor growth." (PMID 35582223, 2020). "Treatment of prostate cancer cells with abiraterone or enzalutamide all increase AKR1C3 expression consistent with androgen-dependent repression of the AKR1C3 gene." (PMID 35582223, 2020). "AKR1C3, which is also involved in arachidonic acid metabolism, plays a role in the progression of prostate cancer and its resistance to hormone therapy." (PMID 31447885, 2019). "Sekine et.al reported that combination of simvastatin and MA suppressed the proliferation of prostate cancer cells through inhibition of the expression of aldo-keto reductase family 1 member C3 (AKR1C3)." (PMID 31333841, 2019). "In conclusion, we found that overexpression of AKR1C3 significantly enhanced human prostate cancer cells resistance to radiation through activation of MAPK pathway." (PMID 27385003, 2016). "The results demonstrated that overexpression of AKR1C3 in prostate cancer can result in radioresistance and suppression of AKR1C3 via its chemical inhibitor indocin restored the sensitivity of the acquired tumor cells." (PMID 27385003, 2016). "AKR1C3 plays an important role in androgen biosynthesis in prostate cancer cells to promote the progression of PCa and its resistance to hormone therapy." (PMID 27385003, 2016). "A previous study showed that AKR1C3 mRNA and protein were overexpressed in castration-resistant prostate cancer tissue as compared to benign prostate and primary prostate cancer tissue." (PMID 24934327, 2015). "Elevated expression of AKR1C3 has been frequently found in human malignancies, such as renal carcinoma, prostate cancer and breast cancer." (PMID 25419901, 2014). "Several studies indicate that AKR1C3 is overexpressed in prostate cancer and its expression increases with the disease progression." (PMID 23359804, 2013). "In conclusion, our results further support previous findings that AKR1C3 play an important role in the androgen metabolism and in the etiology of prostate cancer." (PMID 22888320, 2012). "The overall aim of this study is to increase the understanding on how AKR1C3 is genetically regulated and its putative role in prostate cancer." (PMID 22888320, 2012). "In the prostate, low or undetectable levels of AKR1C3 are observed in normal prostate epithelium, whereas levels of AKR1C3 expression are significantly elevated in localized, advanced, and recurrent prostate cancer (PCa)." (PMID 21134280, 2010).